VHL (von Hippel-Lindau tumor suppressor)
Diseases named in the same sentence as VHL in open-access papers (continued):
Sharing a sentence is not in itself a finding about the gene and the disease.
tumor (continued). "Genomic analyses confirmed VHL loss of heterozygosity in all tumours resulting from the combination of the germline variant and somatic 3p loss in line with previous observations." (PMID 41241877, 2025). "The broad distribution of the VHL variants in the context of personal and family history or VHL tumor status highlights the inefficiency of assessing the evidence in isolation and the need for an integrated evaluation of evidence using INT2GRATE." (PMID 40647474, 2025). "Local tumor control in sHBs is strongly influenced by the EoR, with CR being critical in both sporadic and VHL-associated cases." (PMID 39950840, 2025). "A significant anti-tumor response in VHL-associated RCC was observed with 49% best responses (95% CI: 35-62) at the 21.8-month follow-up, which increased to 64% at the 39-month follow-up." (PMID 41458689, 2025). "We detected the variant c.481C>T (p.Arg161Ter) in exon 3 of the VHL gene by the Sanger sequencing method in the DNA from both tumor samples with clearly visible mutant allele peaks, although with a different ratio of the variant/normal alleles." (PMID 40141393, 2025). "The INT2GRATE variant analysis was performed on the germline VHL variants from 133 patients evaluated in a genetics clinic for cancer predisposition, all of whom had tumor data, with a subset also having somatic sequencing data (Cohort 1)." (PMID 40647474, 2025). "VHL is a tumor suppressor gene located on chromosome 3p and is associated with hypoxia-inducible factors, which serve as potent transcriptional proangiogenic factors in RCC carcinogenesis." (PMID 40856833, 2025). "There are only a few reports in the literature of this type of neoplasia and the majority are associated with VHL." (PMID 40918781, 2025). "The VHL gene is a tumor suppressor gene that consists of three coding exons and encodes the VHL protein." (PMID 40826436, 2025). "Their identification of ventral and intramedullary tumor location as predictors of worse outcomes is corroborated in our mixed cohort study of sporadic and VHL-associated cases." (PMID 39950840, 2025). "The inactivation of somatic mutations or deletions in the von Hippel–Lindau (VHL) tumor suppressor gene region (chromosome arm 3p) is strongly associated with bilateral manifestation of younger age (20–40 years)." (PMID 41226668, 2025). "Immune checkpoint inhibitors, which enhance the body’s immune response against tumor cells, are being explored as potential treatments for VHL-associated tumors." (PMID 40937003, 2025). "Loss of the tumour suppressor Von Hippel–Lindau (VHL) in ccRCC tumours activates the hypoxia response pathway of the cell, leading to induction of VEGF-mediated angiogenesis." (PMID 40295487, 2025). "Clinical studies have shown the efficacy of agents like pazopanib and intravenous bevacizumab in treating advanced HBs, including VHL-associated and recurrent cases, demonstrating tumor reduction, edema reduction, and improved survival." (PMID 40171270, 2025). "Tumor spheroids were generated from parental 786-O (VHL-mutated) and 786-O-pVHL (VHL-restored) ccRCC cell lines." (PMID 40736709, 2025). "The majority cases of ccRCC (>90%) are caused by loss-of-function mutations in the VHL tumor suppressor gene leading to stabilization and activation of hypoxia-inducible factor 2α (HIF-2α)." (PMID 40120683, 2025). "Sanger sequencing demonstrated that the AN2 cells are heterozygous for 481 C>T nonsense mutation in exon 3 of the VHL gene, and the tumor counterpart RCC2 is hemizygous." (PMID 41301058, 2025). "Compound 13 induced cytotoxicity and reduced tumor growth in VHL-deficient RCC cells compared to VHL wild-type (WT) cells." (PMID 40941984, 2025). "The genomic region of 3p loss encompasses four well-recognized tumor suppressor genes (VHL, PBRM1, BAP1, and SETD2)." (PMID 39920694, 2025). "VHL disease is caused by germlinedefects in the VHL tumor suppressor gene, which is located onchromosome 3p25-p26 and has three exons." (PMID 39945572, 2025).
tumor (continued). "The loss of VHL expression can contribute to increased lymphatic invasion as an indicator of tumor spread through the lymphatic system, thereby worsening the overall clinical outcome of cancer." (PMID 40005423, 2025). "With appropriate validation, the data have important implications for risk assessment and decision making in tumor prevention for carriers of the respective VHL mutations." (PMID 40202835, 2025). "CcRCC is characterized by increased expression of genes that promote fatty acid synthesis and glycolysis due to HIF1α and HIF2α activation resulting from the near universal loss of the VHL tumor suppressor gene." (PMID 39874221, 2025). "The excessive activation of HIF1α in cancer, despite oxygen availability, is often driven by oncogenes (e.g., ERBB2, PI3K, Ras, protein kinase B/AKT, mTOR) and mutations in tumour suppressors (e.g., Von Hippel–Lindau (VHL) and PTEN)." (PMID 41007296, 2025). "Loss of the tumour suppressive role of the VHL protein (pVHL) leads to accumulation and constitutive activation of hypoxia inducible factor 1α (HIF-1α), which is responsible for the metabolic switch that allows survival of cells in the hypoxic environment." (PMID 40869272, 2025). "This study provides insights into the management of CNS hemangioblastomas, particularly in VHL-associated cases, emphasizing the balance between tumor control and minimizing treatment-related morbidity." (PMID 40091097, 2025). "ccRCC with VHL missense mutations exhibits distinct oncogenic features, including hyperactivation of cell cycle and NF-κB pathways, contributing to an inflamed tumor microenvironment." (PMID 40909272, 2025). "In conclusion, the INT2GRATE|VHL presents a novel and comprehensive evidence-based framework that integrates germline, somatic, tumor, and associated clinical data, making them publicly accessible via the INT2GRATE variant portal." (PMID 40647474, 2025). "Conversely, among the 24 individuals who met the clinical VHL criteria, 12 patients (50%) harbored a VHL mutation in the tumor." (PMID 40393028, 2025). "The most common VHL-associated neoplasms were CNS HB (88%), RCC (72%), retinal HB (40%) and pNET (40%)." (PMID 40937004, 2025). "Next, to evaluate the synthetic lethal effect of anti-microtubule agents in vivo, we performed mouse tumor xenograft experiments for SKPin C1 and vinorelbine with VHL-deficient 786-O cells." (PMID 40384876, 2025). "Von Hippel–Lindau (VHL) disease is a rare autosomal dominant syndrome, affecting 1:36,000 people, caused by germline inactivation of the VHL tumor suppressor gene." (PMID 40937004, 2025). "Since mTOR is a major inducer of cell growth and proliferation, loss of VHL function can lead to increased mTOR signaling and tumor growth." (PMID 39920694, 2025). "The inactivation of the second allele of the VHL gene in tumor tissue is correlated with benign and malignant tumors, affecting various systems, including the central nervous system and visceral organs." (PMID 39470609, 2025). "Germline inactivation of the von Hippel–Lindau (VHL) tumor suppressor gene causes the autosomal-dominant inherited von Hippel–Lindau tumor disease." (PMID 40202835, 2025). "Chromosome 3p loss is observed in more than 90% of sporadic ccRCC cases, leading to the loss of one copy of four key tumor suppressor genes: VHL, PBRM1, BAP1, and SETD2." (PMID 40362354, 2025). "H&E staining revealed more extensive necrotic areas in the Curcumol-treated group, while VHL deficiency reversed these histological changes, consistent with the tumor growth data." (PMID 41008845, 2025). "This variability is influenced by genotype-phenotype correlations, with specific VHL mutations associated with distinct tumor profiles and disease severity." (PMID 40937003, 2025).
tumor (continued). "We analyzed the tumor samples for VHL mutation where a genetic alteration in the VHL was in more than 75% of the ccRCC samples either by allelic deletion or mutations and the rest of the tumors were without genetic mismatch in the VHL gene." (PMID 40332447, 2025). "The VHL gene encodes the pVHL protein, which functions as a tumor suppressor by acting as the substrate recognition component in the ubiquitin E3 ligase complex." (PMID 40005423, 2025). "Recent clinical studies have demonstrated that belzutifan, a small-molecule HIF2α inhibitor, provides significant clinical benefits in the treatment of VHL-associated tumours." (PMID 40435846, 2025). "This academic center experience reinforces the efficacy of belzutifan in controlling VHL-associated neoplasms and highlights its generally favorable long-term safety profile in routine practice." (PMID 40937004, 2025). "Consistent with our findings from in vivo tumor growth delay studies, Gene Ontology analysis showed that VHL deficiency led to the activation of multiple immune-stimulating pathways." (PMID 39050705, 2024). "Biallelic inactivation of the VHL tumour suppressor gene at chromosome 3p25 is a hallmark event in the development of ccRCC tumours." (PMID 39282259, 2024). "Given the underlying histological and molecular similitudes between sporadic and VHL-associated HBLs, the difference in outcomes is plausibly due to tumor volume at time of treatment and by the fact sporadic lesions harbor cystic components at a higher rate." (PMID 39057165, 2024). "VHL deficiency in ccRCC specimens resulted in elevated levels of autophagy compared to WT VHL-expressing tumor tissues and was associated with poor prognosis of the patients." (PMID 38360997, 2024). "Somatic mutation in the other copy of the VHL gene (second hit or event) initiates tumor development in a particular cell." (PMID 39272694, 2024). "Here, we undertake genome-wide CRISPR/Cas9 screening to reveal synthetic lethal interactors of VHL, and uncover that loss of Core Binding Factor β (CBF-β) causes cell death in VHL-null ccRCC cell lines and impairs tumour establishment and growth in vivo." (PMID 39282259, 2024). "VHL is classified as a tumor suppressor gene, therefore mutations that inactivate this gene predispose VHL patients to neoplasm generation and subsequent tumor formation." (PMID 37883464, 2024). "This strategic adaptation sought to capitalize on the advantageous properties associated with VHL-type ligands, thus enhancing the anti-tumor activity of PROTAC." (PMID 39684655, 2024). "VHL is a genetic disease that predisposes an individual to cysts and tumor formations within the retina, central nervous system, adrenal glands and kidneys." (PMID 37883464, 2024). "Von Hippel-Lindau (VHL) is a tumor suppressor, and mutations in VHL occur in approximately 50% of KIRC patients." (PMID 39125668, 2024). "Pathogenic germline variants in VHL predispose patients to different neoplasias in an autosomal dominant manner, a condition known as VHL disease." (PMID 38969834, 2024). "AXL expression was closely associated with tumor PD-L1 expression, particularly in tumors with VHL gene inactivation." (PMID 39014460, 2024). "Von Hippel–Lindau (VHL) is an autosomal dominant syndrome due to mutations of the VHL gene, a tumor suppressor gene located at chromosome 3p25 that predisposes individuals to the development of multiple benign and malignant neoplasms." (PMID 38893191, 2024). "Our group and others have assessed the role of VHL loss in T cell-mediated anti-viral and anti-tumour activity." (PMID 38690263, 2024). "Genetics: VHL disease is caused by mutations in the VHL tumor suppressor gene located on chromosome 3." (PMID 39272694, 2024). "The panel NGS of the primary tumor revealed pathogenic mutations in VHL, BAP1 and NF2 and likely pathogenic mutations in KDM6A, as well as ABL." (PMID 38611655, 2024).
tumor (continued). "In pre-clinical models, treatment with PT2399 and a CDK4/6 inhibitor resulted in synergistic anti-tumor activity in VHL-deficient ccRCC cell cultures and xenografts." (PMID 38339352, 2024). "The risk that a given VHL disease family will manifest some or all these tumor types is profoundly influenced by the VHL allele it carries." (PMID 39320914, 2024). "Loss of exon 2 leads to sporadic RCC, and approximately half of all VHL tumor mutations have been found to occur here." (PMID 39352796, 2024). "ccRCC is always accompanied with the VHL inactivation and concurrent loss of primary cilia, which were thought to act as suppressors in tumor progression." (PMID 39389955, 2024). "VHL can play a tumor suppressor role through its encoded pVHL and regulate cell cycle, cell differentiation, placental angiogenesis and embryonic development." (PMID 39935706, 2024). "Loss of VHL protein function results in increased cell proliferation, angiogenesis, and tumor progression." (PMID 39886373, 2024). "ccRCC is often associated with the deletion or mutation of the VHL gene, enhancement of glucose and lipid metabolism, and heterogeneity of the tumor microenvironment." (PMID 39399506, 2024). "Next, tumor sequencing data from cBioPortal1,2 were used to examine the functional effects of VHL mutations across human cancers." (PMID 38969834, 2024). "The hypoxia response pathway is activated by hypoxia or VHL mutations in the tumor microenvironment." (PMID 38571885, 2024). "In fact, the paradoxical roles of VHL mutations in promoting tumor development while making them susceptible to ICB therapy are not unique." (PMID 39050705, 2024). "The substantial tumor growth delay caused by VHL gene loss and its synergy with αPD1 treatment led us to posit that VHL played a critical role in regulating the TIME." (PMID 39050705, 2024). "A major challenge in clinical practice is determining tumor risk from a given mutation in the VHL gene." (PMID 37883464, 2024). "Conversely, CAIX is expressed in the vast majority of CRCCs through ubiquination-independent HIF-1α and 2α accumulation due to hypoxia or inactivating mutations in the VHL tumor suppressor gene." (PMID 38791935, 2024). "The observed effects of loss of Vhl in kidney cells provide insights into VHL tumor suppressor action and development of renal cell carcinoma." (PMID 38502859, 2024). "Biallelic inactivation of the VHL tumor suppressor encoded on chromosome 3p25-26 is a hallmark of ccRCC." (PMID 37999735, 2024). "In another case study with metastatic clear renal cell carcinoma, ccfDNA was investigated, and changes in variant allele frequency (VAF) of VHL mutation were associated with the tumor size assessed by radiographic images." (PMID 38893191, 2024). "The loss of both functional VHL alleles within a single cell predisposes an individual to tumor formation occurring from said cell, with one of the most common types of tumor developing being ccRCC." (PMID 37883464, 2024). "constructed a generic DL framework that investigated the mutation status of VHL using only tumor region features and achieved an AUROC of 0.71." (PMID 39166457, 2024). "Tumor cells in ccRCC exhibit von Hippel–Lindau (VHL) tumor suppressor gene loss either by mutation or methylation." (PMID 39585048, 2024). "In this study, we demonstrate that VHL loss enhances the efficacy of anti-programmed death 1 (PD1) treatment in multiple murine tumor models in a T cell-dependent manner." (PMID 39050705, 2024). "Increased VEGF expression is a characteristic feature of all VHL tumor types, and HIF dysregulation has been implicated in this phenomenon." (PMID 38339335, 2024).
tumor (continued). "How do we reconcile the paradoxical roles of VHL loss, which promote tumor development in certain cancers, including ccRCC, and also predispose better response of tumors to ICB therapy?" (PMID 39050705, 2024). "Regarding the VHL gene, variants result in the loss of regulation of the hypoxia-inducible factor, leading to tumour development and metastasis." (PMID 39596125, 2024). "Our results indicated that SSL‐ABMIL can effectively extract histological features for predicting TMB and VHL mutation, demonstrating promising results in linking tumor morphology and molecular biology." (PMID 39166457, 2024). "Loss of VHL stabilizes the protein levels of the hypoxia­inducible factors, HIF1α and HIF2α, resulting in oxygen loss and tumor cell pseudohypoxia." (PMID 38191389, 2024). "Function scores for 2,268 VHL SNVs identify a core set of pathogenic alleles driving ccRCC with perfect accuracy, inform differential risk across tumor types and reveal new mechanisms by which variants impact function." (PMID 38969834, 2024). "Conversely, in VHL mutation, the model exhibited more dispersed attention, allocating same attention to the non‐tumor region, particularly the stromal area infiltrated by lymphocytes." (PMID 39166457, 2024). "In view of the prevalence of VHL mutations in ccRCC, we focus on VHL gene to examine in detail its potential roles in modulating tumor responses to ICB therapy." (PMID 39050705, 2024). "The biophysical attributes of VHL mutations were then examined, in order to provide insight into the molecular characteristics that contribute to tumor formation." (PMID 37883464, 2024). "Pazopanib (NCT01436227) and belzutifan (NCT03401788) were associated with tumor size reduction and disease stabilization in VHL-related conditions." (PMID 39272694, 2024). "TB AAV-VHL effectively restored VHL and decreased leptin expression in adipocytes of tumour-bearing mice, and reversed tumour-associated adipose tissue lipolysis and browning." (PMID 37620316, 2023). "More recent data on tumor heterogeneity highlighted that ccRCC has both cells with a VHL loss-of-function mutation, and cells that retain VHL function." (PMID 37887570, 2023). "Von Hippel–Lindau (VHL) disease is an autosomal dominant tumoral syndrome caused by germline mutations of the VHL tumour suppressor gene (NC_000003.12) situated at chromosome 3 (3p25-p26)." (PMID 37843608, 2023). "In the TCGA-KIRC tumour samples, increasing VHL copy number loss was associated with a significant increase in the HIF composite score (P = 7 × 10−6), whereas an inverse association was seen for the AHR composite score (P = 5 × 10−11)." (PMID 36725335, 2023). "FTO contributes to the loss of the von Hippel-Lindau (VHL) tumour suppressor in clear cell renal cell carcinoma (ccRCC)." (PMID 36859310, 2023). "Massive DNA sequencing of the WBC (germ line) revealed a pathogenic mutation in CHEK2 and the complete loss of a VHL allele (both tumour suppressors)." (PMID 37843608, 2023). "At least theoretically, the initial stages of tumor chronology generate a homogeneous cell growth driven by a VHL gene mutation." (PMID 38136439, 2023). "The protein encoded by the VHL gene (pVHL) mediates its tumour-suppressive effect by binding to and mediating the proteasomal degradation of the hypoxia-inducible factor HIFα." (PMID 38003482, 2023). "Genetically, people predisposed to RCC largely harbor defective von Hippel‒Lindau (VHL), a tumor suppressor gene encoding a type of E3 ubiquitin ligase." (PMID 38072043, 2023). "HIF-α-dependent functions of VHL protein and their association with cellular processes involved in tumor development and progression." (PMID 36036061, 2023). "Fortunately, the opposite effect to the present case was produced since the tumour development due to a VHL mutation was counteracted by a germ line mutation in heterozygous condition at the CLN5 gene." (PMID 37843608, 2023).